SYMPK (symplekin scaffold protein)
Description:
Scaffold protein that functions as a component of a multimolecular complex involved in histone mRNA 3'-end processing. Specific component of the tight junction (TJ) plaque, but might not be an exclusively junctional component. May have a house-keeping rule. Is involved in pre-mRNA polyadenylation. Enhances SSU72 phosphatase activity.
Synonyms: SPK; SYM; Pta1
Tractability: Small molecule: it has a binding pocket of medium quality. Antibody: its Gene Ontology location is reachable by antibodies, with high confidence; UniProt places it where antibodies can reach, with medium confidence; the Human Protein Atlas places it where antibodies can reach. PROTAC: UniProt records ubiquitination sites on it; ubiquitination databases record sites on it; its protein half-life has been measured.
Target class: Structural protein
Gene: Protein-coding gene on chromosome 19 (45,815,410 to 45,866,862, reverse strand). Ensembl gene ENSG00000125755.
Subcellular location: Cytoplasm, cytoskeleton; Cell junction, tight junction; Cell membrane; Cell junction; Nucleus, nucleoplasm
Subcellular location (Human Protein Atlas): Nucleoplasm; Cytosol; Plasma membrane
Pathways (Reactome):
Metabolism of RNA: Processing of Intronless Pre-mRNAs; Transport of Mature mRNA Derived from an Intronless Transcript; mRNA 3'-end processing; mRNA Polyadenylation
Disease: Dengue Virus-Host Interactions
Gene expression (Transcription): RNA Polymerase II Transcription Termination
Gene Ontology:
Molecular function: protein binding
Biological process: mRNA 3'-end processing; negative regulation of protein binding; nuclear histone mRNA catabolic process
Cellular component: cytoplasm; mRNA cleavage and polyadenylation specificity factor complex; nuclear stress granule; nucleoplasm; plasma membrane; mRNA cleavage factor complex; nucleus; anchoring junction; bicellular tight junction; cytoskeleton; nuclear body
Genetic constraint (gnomAD): Loss-of-function variants: 50 observed, 130.09 expected, observed/expected ratio (o/e) 0.38, 90% interval 0.31 to 0.49. The upper end of that interval is the gene's LOEUF score, 0.49, which puts it in group 2 of 6, group 1 being the genes least tolerant of losing a copy. Missense variants: 1,365 observed, 1,671.9 expected, observed/expected ratio (o/e) 0.82, 90% interval 0.78 to 0.85. Synonymous variants: 766 observed, 710.36 expected, observed/expected ratio (o/e) 1.08, 90% interval 1.01 to 1.14.
Homologues: Orthologues: chimpanzee SYMPK (99% identical), macaque SYMPK (99% identical), pig SYMPK (97% identical), dog SYMPK (96% identical), rat Sympk (95% identical), mouse Sympk (94% identical), guinea pig SYMPK (92% identical), rabbit SYMPK (75% identical), tropical clawed frog sympk (67% identical), zebrafish sympk (66% identical), Drosophila melanogaster Sym (33% identical), Caenorhabditis elegans symk-1 (26% identical).
Diseases named in the same sentence as SYMPK in open-access papers:
SYMPK is named in the same sentence as 4 diseases in open-access papers, as found by Europe PMC text mining. Sharing a sentence is not in itself a finding about the gene and the disease. The quoted sentences say what the papers report.
breast carcinoma (1 paper, 2018). "SOAT mRNA expression was normalized by SYMPK expression, which has previously demonstrated particularly low variability of expression in breast cancer tissue and cell lines." (PMID 30186172, 2018).
cancer (1 paper, 2025). A tumor composed of atypical neoplastic, often pleomorphic cells that invade other tissues. "We found that many CPA genes are mutated in cancer, notably PCF11, WDR33, CPSF1, and SYMPK." (PMID 41463412, 2025).
SYMPK also shares sentences with these, for which no sentence is quoted: tumor (2 papers); type 1 diabetes mellitus (1).